CDK4 (cyclin dependent kinase 4)
Diseases named in the same sentence as CDK4 in open-access papers (continued):
Sharing a sentence is not in itself a finding about the gene and the disease.
lung cancer (194 papers, 2010 to 2025). A malignant neoplasm involving the lung. "Deletion of CDK4 caused cell cycle arrest and promoted cell senescence in lung cancer cells with the endogenous K-RAS oncogene." (PMID 36838737, 2023). "The upregulation of cyclin-dependent kinase 4 (CDK4) was also reported to mediate acquired resistance to dabrafenib combined trametinib in lung cancer patients with BRAF V600E mutation." (PMID 36508072, 2022). "UA232 treatment of lung cancer cells caused the cells to arrest in the G0/G1 phase of the cell cycle in association with downregulation of cyclin D1 and CDK4." (PMID 36364289, 2022). "Acquired resistance to MEK inhibition in lung cancer has previously been associated with p16/RB1/CDK4 regulatory status." (PMID 36418460, 2022). "Previous studies demonstrated that FOXK2 suppressed the growth of lung cancer cells by targeting cyclin D1 and CDK4 and also influenced CDKs, which linked it to the regulation of the cell cycle." (PMID 33251211, 2020). "SMARCA4 loss results in low levels of cyclin-dependent kinase 4/6 (CDK4/6) inhibitor p16INK4a in lung cancer." (PMID 31238554, 2019). "CDK4 expression patterns had been reported to be associated with clinical pathology parameters in some tumors including lung cancer, osteosarcomas, colorectal cancer, and chondrosarcomas." (PMID 24751144, 2014). "To investigate the prognostic value of CDK4 expression for lung cancer, we assessed the association between the expression levels and patient survival using Kaplan-Meier analysis with the log-rank test." (PMID 21477379, 2011). "This increased CDK4 expression was associated with the progression and poor prognosis of lung cancer patients." (PMID 21477379, 2011). "Increased CHK1/2 activity by Tax during S phase restricts the CDK-dependent phosphorylation of FOXM1, preventing the premature expression of G2/M genes, including those encoding cyclin-dependent kinase 4, cyclin B1, and cyclin A2, all common DEGs in lung cancer." (PMID 39228892, 2024). "Thus, it is hypothesized that loss of STK11 in lung cancer may lead to enhanced dependency on upregulated CDK4." (PMID 28205554, 2017). "In preclinical models of lung cancer, CDK4/6 and MEK inhibition induced cellular senescence and an inflammatory transcriptional program called the senescence-associated secretory phenotype (SASP)." (PMID 40723291, 2025). "Studies on other malignancies, including adrenocortical carcinoma, osteosarcoma, lung cancer, and nasopharyngeal carcinoma, have demonstrated overexpression of CDK4 and CDK6, which promote tumor progression and poor prognosis." (PMID 40304827, 2025). "As in their studies of lung cancer, CDK4/6 and MEK inhibitors suppressed PDAC proliferation and induced SASP in vivo." (PMID 40723291, 2025). "In non-small cell lung carcinoma, piR-651 increased the expression of Cyclin D1 and CDK4 to promote tumor progression, while piR-55490 inhibited cell proliferation in lung cancer cells by targeting the 3′ UTR (untranslated region) of mTOR mRNA." (PMID 41154843, 2025). "Lung cancer cells resistant to the CDK4/6 inhibitor palbociclib exhibit increased sensitivity to FGFR (fibroblast growth factor receptor) inhibition." (PMID 40563591, 2025). "In their Ras mutant lung cancer model, CDK4/6 and MEK inhibition prolonged mouse survival in an NK cell- and SASP-dependent manner." (PMID 40723291, 2025). "It was shown that C. gigantea inhibits the growth of human lung cancer cells by downregulating the genes Akt, CDK4, CCND1, and CCND2, which are important for cell cycle arrest in the G1/S phase." (PMID 40142097, 2025). "Elevated RTK activity has been observed in lung cancer cells exhibiting resistance to CDK4/6 inhibitors." (PMID 40563591, 2025).
lung cancer (continued). "Mechanistically, we revealed that DDX18 promotes lung cancer cell cycle progression through transcriptional activation of CDK4." (PMID 38732173, 2024). "By targeting DDX18 and its ability to regulate CDK4 expression and influence cell cycle progression, we can potentially develop novel therapeutic strategies to impede lung cancer growth." (PMID 38732173, 2024). "In non‐small cell lung cancer cells, Amentoflavone treatment significantly increases the cell population at the G1/G0 phase by decreasing the expression of cyclin D1, CDK4, and CDK6 in both H358 and H1299 cells." (PMID 38842135, 2024). "Reports suggest that inhibiting cMyc halts lung cancer cell growth by inhibiting cyclin-dependent kinases, such as CDK4/6 and CDC2." (PMID 39518013, 2024). "Targeting both the MEK-ERK pathway and CDK4/6 with the MEK inhibitor selumetinib combined with the CDK4/6 inhibitor palbociclib was shown to have a synergistic antitumoral effect in a lung cancer xenograft model with concomitant RAS and CDKN2A alterations." (PMID 39352477, 2024). "In our study, we found that MH inhibited the growth of lung cancer cells by lowering the expression of cMYC and cell cycle regulatory proteins CDK4/6 and CDC2." (PMID 39518013, 2024). "Our findings provide compelling evidence that DDX18 depletion induces G1 phase arrest in lung cancer cells, coinciding with a decrease in CDK4 protein expression." (PMID 38732173, 2024). "Here, we demonstrate that Leucine Rich Pentatricopeptide Repeat Containing (LRPPRC) controls CDK4/6i response in lung cancer by forming a feedback loop with CDK6." (PMID 37452037, 2023). "The combination of trametinib and CDK4/6 inhibitors in KRAS-mutated solid tumors, including PDAC, lung cancer, and colorectal cancer, also elicited a robust therapeutic response." (PMID 37817078, 2023). "The approval of the CDK4/6 inhibitor trilaciclib for myeloprotection in patients with lung cancer shows that it is possible." (PMID 36913303, 2023). "In clinical practice, lung cancer patients expressing a high level of CDK6 showed significant resistance towards CDK4/6i16." (PMID 37452037, 2023). "Here the authors show that Lkb1-deficient lung tumors are characterized by defective trafficking and adhesion of T cells and that, by upregulating ICAM1 expression, CDK4/6 inhibitors sensitize LKB1 mutant lung cancer to anti-PD1 blockade." (PMID 36871040, 2023). "According to our results, CDK4 was colocalized with CKMT1 in mitochondria of lung cancer cells and its phosphorylation level is also regulated by CKMT1." (PMID 37061730, 2023). "Considering that CDK4/6/Rb pathways are frequently upregulated in the lung cancer patients, CDK4/6 inhibitors are considered as a safe and effective strategy for treating lung cancer." (PMID 35814226, 2022). "CDK4 had been reported to be related to a poor prognosis of osteosarcoma, triple-negative breast cancer, elderly lung cancer, and nasopharyngeal carcinoma." (PMID 35193513, 2022). "Of note, dysregulations of cell cycle are detected in over 90% of lung cancers, and aberrant alteration of CDK4/6 pathways are detected in all lung cancer patients." (PMID 35814226, 2022). "Currently, FDA-approved CDK4/6 inhibitors, including ribociclib, abemaciclib and palbociclib, have significant therapeutic activity against lung cancer cells in the preclinical studies." (PMID 35814226, 2022). "miRNA-545-3p has been reported to induce cell cycle arrest and apoptosis in lung cancer by regulating CDK4 and cyclin D1." (PMID 35260044, 2022). "Human A549 and H460 lung cancer cells treated with UA exhibited reduced proliferation, as well as reduced CDK4, cyclin D1 and cyclin E protein and mRNA levels, whereas the levels of p21 and p27 tumor suppressor proteins were increased." (PMID 36364289, 2022). "For example, we found RB1 mutation was associated with resistance to Palbociclib, a highly selective inhibitor of CDK4/6, in lung cancer cells." (PMID 36180906, 2022).
lung cancer (continued). "Because mTOR inhibitors in combination with CDK4/6 inhibitors was reported, we thus investigated the effect of the combination of abemaciclib and gilteritinib in lung cancer cells." (PMID 35814226, 2022). "In the current work, we demonstrated that BHGJT inhibited lung cancer growth by inducing cell cycle arrest via the downregulation of CDK4 and Cyclin D1 and apoptosis via the AKT/GSK3β/β-catenin signaling pathways." (PMID 34659548, 2021). "With an understanding of how lung cancer cells adapt to therapeutic intervention, we interrogated the combination of CDK4 and MEK inhibitors." (PMID 34309585, 2021). "Some studies have shown that CDK4 and cyclin D1 expression is correlated with the presence of KRAS mutation in lung tumors, and a synthetic lethal interaction occurs between KRAS and CDK4 in lung cancer tumor progression." (PMID 34309585, 2021). "Both human and murine mesenchymal-like lung cancer were more sensitive to CDK4 inhibitors (palbociclib, abemaciclib, and ribociclib)." (PMID 34309585, 2021). "We treated a panel of human and murine lung cancer cells, stratified as epithelial-like or mesenchymal-like based on previous profiling, with CDK4 inhibitors." (PMID 34309585, 2021). "On the one hand, we found that licorice down-regulates CDK4-Cyclin D1 complex, resulting in G0/G1 phase arrest and increased PD-L1 levels in lung cancer cells." (PMID 34641869, 2021). "A panel of epithelial cell–like and mesenchymal-like murine lung cancer cells were tested, and the mesenchymal-like cells demonstrated higher Cdk4 mRNA levels." (PMID 34309585, 2021). "Partial response to CDK4 inhibitor in a subset of lung cancer patients warranted an exploration of combination with other targeted therapies." (PMID 34309585, 2021). "Our detailed investigation shows that licorice induces G1 cell-cycle arrest in lung cancer cells by inhibiting CDK4-Cyclin D1 complex, which in turn increases antigen presentation and results in intra-tumoral CD8+ T cell infiltration but increase PD-L1 levels." (PMID 34641869, 2021). "The therapeutic potential of targeting cyclin-dependent kinases, such as CDK4/6 and Cyclin D, has been recognized, and several inhibitors, such as palbociclib and ribociclib, have been approved for the treatment of lung cancer." (PMID 34659548, 2021). "We next explored the effect of p21 on CDK4 activity in epithelial and mesenchymal lung cancer cells." (PMID 34309585, 2021). "CDK4 mRNA expression showed a positive correlation with a previously reported 76-gene EMT signature in 118 human non–small cell lung cancer (NSCLC) cell lines." (PMID 34309585, 2021). "So, we concluded that licorice induces G1 cell-cycle block in lung cancer cells by inhibiting CDK4-Cyclin D1 complex, which in turn increase antigen presentation and results in intra-tumoral CD8+ T cell infiltration." (PMID 34641869, 2021). "Our study sheds new light onto the mechanisms of osimertinib resistance and provides a rationale for targeting CDK4/6 as a potential therapy in overcoming third‐generation EGFR‐TKIs in lung cancer treatment." (PMID 32677256, 2020). "Our stapled P2short peptide thus constitutes an attractive means of sensitizing CDK4 to ATP-competitive therapeutics for the treatment of KRAS-mutant lung cancer patients." (PMID 32104498, 2020). "Lastly, P10 had a CDK4 gene amplification exclusively in the BM biopsy which is treatable by the level B non lung cancer drug Abelaciclib." (PMID 32942985, 2020). "Suppression of CTNNB1 downregulates its downstream transcriptional targets (c-Myc, Cyclin D1, and CDK4) and suppresses the proliferation of lung cancer cells." (PMID 33268793, 2020). "Taken together these data highlight a correlation between cyclin D1/CDK4 expression and KRAS mutation in lung ADC, suggesting enhanced activation of CDK4/Cyclin D in KRAS mutant lung cancer." (PMID 32104498, 2020). "Here, we showed that expression of CDK4 and phosphorylation of Rb were increased in osimertinib‐resistant lung cancer cells." (PMID 32677256, 2020).
lung cancer (continued). "As was previously shown by proteomic analysis of lung carcinoma cells, the knockdown of YTHDF1 led to activation of cell cycle inhibitor p27Kip1 and suppression of cell cycle activator genes encoding CDK2, CDK4 and cyclin D1." (PMID 33317545, 2020). "We identify CDK4 as a synthetic vulnerability in colorectal cancer cells and show that dual inhibition of TNKS and CDK4 drives a potent cell cycle arrest in a range of human epithelial cancer cell lines including colon, breast and lung cancer cells." (PMID 31891587, 2019). "Especially, the identified genes EGFR, CDKN2A, ERBB2, RB1, and CDK4 were significantly enriched for non‐small cell lung cancer, demonstrating that UniCovEx accurately identified the cancer‐related gene modules." (PMID 30828525, 2019). "An in vitro analysis has shown that miR-503-3p induces apoptosis of lung cancer cells by downregulating p21cip1/waf1 and CDK4 expression." (PMID 31514410, 2019). "As expected, decreases in cyclin D1 and CDK4 were found in the lung cancer cells after the tetracenomycin X treatment." (PMID 30669360, 2019). "Here, we investigated this synthetic lethal interaction in SMARCA4-deficient NSCLC, which has a complex mutation landscape, and explored the potential strategy of using CDK4/6 inhibitors to treat this highly aggressive subgroup of lung cancer." (PMID 30718506, 2019). "Doses of tetracenomycin X at 2.5 and 5 μmol/L abated the levels of cyclin D1 and CDK4 (cyclin-dependent kinase 4) in the five lung cancer cells." (PMID 30669360, 2019). "SOX9 affects the expression of the cell cycle regulators p21 and cyclin-dependent kinase 4 and thus contributes to an increase in lung cancer growth potential." (PMID 31379926, 2019). "The concept that the G1 cell cycle kinases CDK4/6 interfere with cell migration and cytoskeletal organisation has already been suggested: recent publications assigned a role to CDK4 in lung cancer cells." (PMID 30858922, 2019). "Our results show that 2HF induced apoptosis in both histological types of lung cancer and inhibited proliferation and growth through suppression of CDK4, CCNB1, PIK3CA, AKT and RPS6KB1 (P70S6K) signaling." (PMID 30546837, 2018). "Our study shows that CDK4/6 inhibitors, even at sublethal concentrations, cause a considerable decrease in PARP1 transcription, in addition to suppressing lung cancer cell growth." (PMID 29306194, 2018). "In summary, inhibitors of CDK4/6 sensitize lung cancer cells to oxidative stress-inducing anticancer drugs by creating a functional link between RB1, PARP1, and OGG1." (PMID 29306194, 2018). "Based on these preclinical data demonstrating synergy of palbociclib in combination with everolimus, and the demonstrated tolerability of palbociclib in patients with advanced lung cancer, a clinical trial with combined CDK4/6 and mTOR inhibition is warranted." (PMID 30647837, 2018). "The epistatic retinoblastoma (RB: CDK4/6: Cyclin D: CDKN2a/p16) signaling pathway is targeted for somatic or epigenetic alterations in essentially 100% of lung cancer samples." (PMID 30647837, 2018). "In lung cancer cells, CDK4/6 inhibition results in suppression of IAPs, FOXM1 and survivin and an augmentation of SMAC and caspase 3 expression." (PMID 30349650, 2018). "CDK4 expression is significantly upregulated in lung cancer tissues and function as an important element for cell proliferation." (PMID 28095789, 2017). "This mechanistic relationship would nominate STK11 mutant lung cancer for therapeutic intervention with CDK4 inhibitors." (PMID 28205554, 2017). "Demonstration of two selected PPIs, MYC/NSD3 and STK11/CDK4, under endogenous conditions in multiple lung cancer cell lines strongly supports the validity of the OncoPPi network data set for further examination." (PMID 28205554, 2017).
lung cancer (continued). "It has been reported that dual inhibition of CDK4/6 inhibitor and gemcitabine enhanced the antitumor effect in a xenograft model of lung cancer and CDK4/6 inhibition also sensitized neuroblastoma cells to doxorubicin-induced apoptosis." (PMID 28578693, 2017). "Endogenous co-immunoprecipitation experiments demonstrated the STK11/CDK4 interaction under physiological conditions in multiple lung cancer cell lines, including H1299 and H1792 cells." (PMID 28205554, 2017). "We show that activation of pRb by treatment of lung carcinoma cells with palbociclib, a CDK4/6 inhibitor, increased the expression of MEG3 in a pRb-specific manner." (PMID 27832204, 2016). "In this study, we observed that CDK4 was mainly coexpressed in the nucleus and cytoplasm in lung cancer and normal lung tissues." (PMID 24751144, 2014). "miR-545 inhibits the proliferation of lung cancer cells by repressing the expression of cyclin D1 and CDK4 genes." (PMID 24505359, 2014). "Western blot results also revealed correlations between the levels of RNF146 in lung cancer cells and the expression of cell cycle-related regulatory proteins including cyclinD1, cyclinE and CDK4." (PMID 24454854, 2014). "Experiments using lentiviral-mediated shRNA to inhibit CDK4 in A549 have shown inhibited cell cycle progression, suppressed cell proliferation, colony formation, and migration, and there is an ongoing clinical trial using a CDK4/6 inhibitor in lung cancer." (PMID 24961498, 2014). "Previous studies report that the expression of cyclin D1 and CDK4 in human lung cancer tissues is substantially higher than that in normal lung tissues." (PMID 24505359, 2014). "We found that miR-545 suppresses cell proliferation by directly targeting cyclin D1 and CDK4 genes in lung cancer cell lines." (PMID 24505359, 2014). "We also found that miR-545 caused cell cycle arrest at the G0/G1 phase and induced cell apoptosis in lung cancer cells by targeting cyclin D1 and CDK4 genes." (PMID 24505359, 2014). "Earlier data from our laboratory has shown that P276-00, a Cdk inhibitor inhibits cyclin D1 and down regulates Cdk4 specific phosphorylation of RB at Ser780 (pRbSer780) along with up regulation of p27 and p21 in breast and lung cancer cell lines." (PMID 23075291, 2012). "In 89 lung cancer cases with prognosis information, we observed that the level of CDK4 protein expression was significantly correlated with the overall survival of lung cancer patients." (PMID 21477379, 2011). "Due to the limited sample size of patients in our investigation, further studies would be needed to verify these findings and establish the role of CDK4 as a reliable clinical predictor for lung cancer outcome." (PMID 21477379, 2011). "Multivariate analyses showed that increased expression of CDK4 protein was a significant predictor of poor prognosis for lung cancer patients." (PMID 21477379, 2011). "We measured the expression levels and subcellular localization of CDK4 protein in 89 archived paraffin-embedded lung cancer samples and 23 normal lung tissues using immunohistochemical staining." (PMID 21477379, 2011). "The expression level of CDK4 protein was significantly increased in lung cancer tissues compared to normal tissues (P < 0.001)." (PMID 21477379, 2011). "To study the biological function of CDK4, we used a lentiviral vector containing shRNA to specifically target and stably knock down the expression of CDK4 in A549 cells, a lung cancer cell line with high endogenous levels." (PMID 21477379, 2011). "Use of lentiviral-mediated shRNA to inhibit the expression of CDK4 in lung cancer cell line A549 not only inhibited cell cycle progression, but also dramatically suppressed cell proliferation, colony formation, and migration." (PMID 21477379, 2011).